RNU6-1041P (RNA, U6 small nuclear 1041, pseudogene)
Gene: Small nuclear RNA gene on chromosome 19 (53,760,087 to 53,760,188, reverse strand). Ensembl gene ENSG00000252063.
Homologues: Orthologues: guinea pig U6 (75% identical). Paralogues in human: RNU6-982P (94% identical), RNU6-980P (84% identical), RNU6-751P (82% identical), RNU6-1145P (81% identical), RNU6-1316P (81% identical), RNU6-20P (81% identical), RNU6-310P (81% identical), RNU6-170P (80% identical), RNU6-38P (80% identical), RNU6-1031P (79% identical), RNU6-1036P (79% identical), RNU6-283P (79% identical), and 1280 more.